CD44 (CD44 molecule (IN blood group))
Diseases named in the same sentence as CD44 in open-access papers (continued):
Sharing a sentence is not in itself a finding about the gene and the disease.
colorectal adenoma (6 papers, 2012 to 2023). An adenoma that arises from the colon or rectum. "We studied expression of variant isoforms of CD44 in precancerous tissue of the large intestine and compared the level of expression of CD44 in adjacent healthy mucosa in a cohort of 50 colorectal adenoma patients." (PMID 34257584, 2021). "In terms of cell surface markers, the presence of CD44 markers on the surface of human colorectal adenoma cell line LT97 was classified." (PMID 37228502, 2023). "In conclusion, the CD44 marker on the surface of human colorectal adenoma cells as well as ERK can be mediated by FGF18 signaling, and Wnt can mediate FGF18 signaling activity." (PMID 37228502, 2023). "CD44, a cancer stem cell marker has been reported to get over-expressed in colorectal adenomas thereby driving them towards carcinoma." (PMID 35642021, 2022). "Our results also show that aberrant splicing of CD44 occurs in both biologically distinct subtypes of colorectal adenoma possibly in ESRP-1 specific manner." (PMID 34257584, 2021). "According with this notion, while the glandular epithelium of the large bowel expresses the standard form of CD44 but not variant ones, in contrast, highly dysplastic colorectal adenomas, primary and metastatic CRC, express CD44v isoforms." (PMID 31139149, 2019).
diabetic retinopathy (6 papers, 2023 to 2025). "have pinpointed six significant genes (CD44, CDC42, TIMP1, BMP7, RHOC, FLT1) as crucial for diabetic retinopathy through advanced bioinformatics analysis coupled with in vivo validation." (PMID 38605967, 2024). "In parallel, Huang and Zhou combined integrative bioinformatics with in vivo validation to uncover critical regulators such as CD44 and CDC42 in the context of diabetic retinopathy, underscoring the translational potential of network-based approaches in ocular disease research." (PMID 40548296, 2025).
gynecological cancers (6 papers, 2010 to 2025). "A tissue microarray of primary tumors from SCCOHT and other gynecological cancers were stained for Claudin-4 and CD44." (PMID 33355532, 2020). "CSCs were isolated from breast, prostate, and ovary tumor cell lines, and characterized using tumor-specific markers such as CD44+/CD24−/CD133+." (PMID 28536422, 2017). "More recently, gynecological cancer initiating cells have been isolated based on either differential expression of a number of surface antigens (CD44+, CD117+ or CD133) or differential exclusion of Hoechst dye." (PMID 21122138, 2010). "Because CD44 plays a pivotal role in promoting tumor metastasis and conferring resistance to therapy, multiple therapeutic strategies have been designed to target CD44 against various cancers, including breast, head and neck, ovarian, and gynecological cancers." (PMID 41369362, 2025).
Hepatitis (6 papers, 2013 to 2025). Inflammation of the liver. "Because CCR2 and its ligands are upregulated in B6 mice and because CD44 expression is increased in LD fed B6 mice we wanted to determine if these two molecules were critical for hepatitis formation in this model." (PMID 23762326, 2013). "A previous study demonstrated that CD44-knockout mice exhibited enhanced pathogenesis in Con A-induced hepatitis, primarily due to inability of Con A-activated CD44-deficient T cells to undergo apoptosis." (PMID 23894507, 2013). "Cd44−/− mice displayed significant hepatitis at 1 and 4 weeks when compared to SD fed controls." (PMID 23762326, 2013). "Ccr2−/− mice were completely protected from hepatitis and Cd44−/− mice were partially protected." (PMID 23762326, 2013). "Therefore, we analyzed whether CCR2 and CD44 gene deleted mice were resistant to LD induced hepatitis." (PMID 23762326, 2013). "From the health to hepatitis, the MIF signaling network and related ligand-receptor interactions, including MIF-(CD74 + CXCR4), MIF-(CD74 + CXCR2), and MIF-(CD74 + CD44) showed a significant effect on macrophage–naïve CD4 + T cell interaction." (PMID 36221095, 2022). "Collectively, our studies show that CD44 and CCR2 contribute to hepatitis in a model of NAFLD despite histological evidence of steatosis and elevated serological markers of hepatocellular damage." (PMID 23762326, 2013). "Our findings reinforce studies in humans that have identified CCR2 and CD44 as being increased in NASH patients and they establish a possible link between these two molecules in lipid mediated hepatitis progression in so far as Ccr2−/− mice are largely protected from CD44 mediated HA binding." (PMID 23762326, 2013).
hepatoblastoma (6 papers, 2018 to 2023). Hepatoblastoma (HB) is a malignant hepatic tumor and is the most common pediatric liver cancer. "MiRNA-492 positively regulates CD44 (CD44s and CD44v10) expression and increases the proliferation, cell adhesion, and invasive ability of hepatoblastoma cells." (PMID 36964570, 2023). "miR-126 downregulation notably attenuated hepatoblastoma tumor growth and decreased the ratio of CD44+ CD90+ CD133+ cells and increased the expression of IL-6, Oct4, SRY, TGF-β, and β-catenin in tumor tissues of mice." (PMID 34746322, 2021). "EVs derived from hepatoblastoma cells significantly increased the ratio of CD44+ CD90+ CD133+ cells and increased the expression of IL-6, Oct4, SRY, and TGF-β in bone marrow mesenchymal stem cells (BMSCs), while EVs with downregulated miR-126 reversed these phenomena." (PMID 34746322, 2021). "This correlation between CD44 expression and the aggressiveness of HCC tumors has been confirmed, in this work, in in vitro experiments performed on HepG2 and Huh7 cells (hepatoblastoma and hepatocarcinoma cell lines, respectively)." (PMID 35164326, 2022).
IgA nephropathy (6 papers, 2013 to 2025). "CD44 is a transmembrane glycoprotein reported to be reduced in urine in conditions such as acute kidney transplant rejection and IgA nephropathy, which aligns with our findings where it was reduced but positively associated with eGFR in the CKD group." (PMID 39858440, 2025). "Renal expression of CD44 is markedly increased in experimental models of kidney injury, and human nephropathies such as IgA nephropathy, crescentic glomerulonephritis and membranoproliferative glomerulonephritis." (PMID 39411720, 2024). "In patients with IgA nephropathy, renal CD44 expression strongly correlated with the degree of glomerular and tubulo-interstitial damage, and proteinuria." (PMID 39411720, 2024). "In the IgA nephropathy group, CD44 moderate expression in the mesangium was observed in nine patients (82%); it was mild in one patient (9%), and absent in one patient (9%)." (PMID 37108355, 2023). "In the IgA nephropathy group, CD44+ PEC moderate expression was observed in two patients (18%), mild expression was observed in six patients (55%), and three patients (27%) did not have any expression." (PMID 37108355, 2023). "In the IgA nephropathy group, CD44 expression III in the interstitium was observed in 10 patients (91%); CD44 expression II was observed in 1 patient (9%)." (PMID 37108355, 2023). "In human IgA nephropathy and in renal allografts, tubular CD44 expression was found to correlate with IF/TA." (PMID 28002484, 2016). "Our analysis also demonstrates decreased urinary excretion of CD44 in more advanced stages of IgA nephropathy." (PMID 24339887, 2013). "In patients with active and progressing IgA nephropathy, strong CD44 MC expression was also shown." (PMID 37108355, 2023). "CD44 is present in four of the biological processes obtained from DAVID, pointing out the importance of this protein in progression of IgA nephropathy." (PMID 24339887, 2013). "Strong CD44 expression was noted predominantly in PEC and mesangial cells (MC) in patients with FSGS, and to a lesser extent, in patients with MN and IgA nephropathy, and it was absent in patients with MCD." (PMID 37108355, 2023).
intestinal tumors (6 papers, 2021 to 2025). "Cd44 was upregulated in the leading cells at the invasive front of the intestinal tumors in cis-Apc+/−Cdx1+/− mice." (PMID 40399276, 2025). "CD44 is reported to be a target gene of Wnt/β-catenin in a mouse intestinal tumor model." (PMID 41009730, 2025). "In addition, CD44 may influence the development of intestinal tumors by activating the Hippo pathway." (PMID 38130953, 2023).
kidney inflammation (6 papers, 2013 to 2024). "CD44 is a glycoprotein that is expressed on immune cells, whereas CSF-1 is a growth factor for macrophages; and both of these genes are upregulated in nephritis." (PMID 31817608, 2019). "Moderate and strong CD44 interstitial expression was found in patients with active nephritis and high proteinuria regardless of histological form." (PMID 37108355, 2023).
kidney stone (6 papers, 2023 to 2025). "The present study showed that after the oxalate-induced HK-2 cell damage, the expression levels of ANXA1 and CD44 proteins are increased, and the adhesion of CaOx crystals on the cell surface is enhanced, thereby increasing the risk of kidney stone formation." (PMID 38204734, 2024). "Crystal adhesion is critical in kidney stone formation, with CD44 and OPN being the most common adhesion molecules." (PMID 41255516, 2025). "Quantitative analysis revealed significantly higher mRNA expression of NLRP3, GSDMD, and crystal adhesion factor (cluster of differentiation 44, CD44) in kidney stone samples than in normal samples." (PMID 40384863, 2025).
mucoepidermoid carcinoma (6 papers, 2015 to 2021). A carcinoma morphologically characterized the presence of cuboidal mucous cells, goblet-like mucous cells, squamoid cells, cystic changes, and a fibrotic stromal formation. "Immunohistochemistry analyses of CD44 expression in mucoepidermoid carcinoma revealed that high CD44 expression was significantly correlated with advanced tumours and increased recurrence or metastasis." (PMID 34944493, 2021). "CD44 showed a low expression in the majority of our carcinoma, mucoepidermoid-carcinoma, and other types of adenocarcinoma as investigated in our cohort." (PMID 33009929, 2021). "Our result showed that mucoepidermoid carcinomas are immunohistochemistry positive to CD44 compare to normal." (PMID 26821610, 2016). "Here, we investigated the expression of putative cancer stem cell markers (ALDH, CD10, CD24, CD44) in primary human mucoepidermoid carcinomas by immunofluorescence, in vitro salisphere assays, and in vivo tumorigenicity assays in immunodeficient mice." (PMID 26449187, 2015). "To investigate the effect of tocilizumab on putative cancer stem cells in vivo, we performed immunofluorescence staining for ALDH1 and CD44 in mucoepidermoid carcinoma xenografts." (PMID 26287605, 2015). "A series of complementary independent in vivo studies demonstrated that the ALDH/CD44 marker combination enriches for cancer stem cells in mucoepidermoid carcinomas." (PMID 26449187, 2015). "We evaluate CD44 expression in different grades of mucoepidermoid carcinoma and determine whether expression of CD44 can be used to predict tumor aggressiveness." (PMID 26821610, 2016). "Further, little is known about the role of CD44 in the progression of mucoepidermoid carcinomas." (PMID 26449187, 2015). "High level expression of CSCs markers such as CD44 has been detected at invasive front in OSCC and mucoepidermoid carcinoma (MEC)." (PMID 31579438, 2019). "Our findings indicate that cancer stem cells play a functional role in mucoepidermoid carcinoma, and that these cells can be isolated using the ALDH/CD44 marker combination." (PMID 26449187, 2015). "Testing of several putative marker combinations demonstrated that cancer stem cells are identified in mucoepidermoid carcinomas by high aldehyde dehydrogenase (ALDH) activity and CD44 expression (ALDHhighCD44high)." (PMID 26287605, 2015).
multiple sclerosis (6 papers, 2021 to 2026). A progressive autoimmune disorder affecting the central nervous system resulting in demyelination. "In addition, CD44 deficient mice have significantly increased blood–brain barrier permeability which severely worsens the progression of multiple sclerosis." (PMID 33964983, 2021). "First, it is most likely involved in the interaction of CD44 with CD49 which represents a co-receptor involved in the homing of bone-marrow-derived cells into the CNS during experimental multiple sclerosis." (PMID 37509083, 2023). "CD44 is mainly involved in the modulation of inflammation and therefore its overexpression in microglia can indicate the neuroinflammation pathogenesis in multiple sclerosis, PD and AD." (PMID 40106490, 2025). "Under pathological conditions such as multiple sclerosis (MS) and its respective experimental model in rodents (Experimental Autoimmune Encephalomyelitis, EAE), CD44 has immunomodulatory properties and protects from the disruption of the BBB." (PMID 35639208, 2022).
oropharyngeal carcinoma (6 papers, 2014 to 2025). Carcinoma, predominantly squamous cell, arising from the epithelial cells of the oropharynx. "This present study aims to investigate the expression of CD44 in oral and oropharyngeal carcinoma and its correlation with clinicopathological factors." (PMID 40291275, 2025). "Our study aimed to examine the expression of CD44 in oral and oropharyngeal carcinoma using immunohistochemistry and compare it across different histological grades." (PMID 40291275, 2025). "In oral and oropharyngeal cancer, different membrane and cytoplasmic CD44 expressions also determined distinct clinical outcomes." (PMID 34063938, 2021). "In total, 67% of all HNSCC cancers, 67% of cancers of the oral cavity, 70% of cancers of the oropharynx, and 63% of cancers of the larynx expressed CD44." (PMID 31661833, 2019).
peritonitis (6 papers, 2015 to 2023). Inflammation of the peritoneum (tissue that lines the abdominal wall and covers most of the organs in the abdomen). "Notably, the well-characterized hyaluronan receptor CD44 was not altered in this context, whereas it was previously shown to display anti-inflammatory properties and the knockout of CD44 in macrophages was associated with higher levels of pro-inflammatory cytokines in a peritonitis model." (PMID 37998039, 2023). "In addition, a previous study demonstrated that TSG-6 attenuates zymosan-induced mouse peritonitis by decreasing TLR2/NF-κB signaling, dependent on the expression of CD44 on macrophages." (PMID 27917949, 2016).
rectal cancer (6 papers, 2014 to 2024). A primary or metastatic malignant neoplasm that affects the rectum. "Treatment that decreases Tregs and increases the expression of CD44 in CD4+ and CD8+ T cells, is able to suppress liver metastases and improve the overall survival rate in rectal cancer." (PMID 37709489, 2023).
sarcoidosis (6 papers, 2023 to 2025). Sarcoidosis is a multisystemic disorder of unknown cause characterized by the formation of immune granulomas in involved organs. "CD4+ T cell subsets were also similarly represented in patients with active and inactive TU, although we observed a small increase in CD44+ effector cells in the sarcoidosis group compared with healthy donors." (PMID 40469525, 2025). "Similar to other forms of sarcoidosis, the expression of RUNX1, MMP9, MMP12, CCR5, ITGAX, CD44, and human leukocyte antigens (HLA) is also seen in the granuloma of CS." (PMID 40521183, 2025). "While MET is a hallmark of tissue granuloma formation, blood monocytes in both active TU and sarcoidosis exhibited epithelial–mesenchymal transition (EMT) signatures, including significantly increased expression of GADD45B, CD44, CXCL8, ANPEP and THBS1,30, 31, 32, 33 compared with healthy donors." (PMID 40469525, 2025). "Some EV markers were common between HP and sarcoidosis (CD11c, CD1c, CD209, CD4, CD40, CD44, CD8)." (PMID 36835481, 2023). "The blood CD4+CD31+ T lymphocyte and CD4+CD44+ T lymphocyte counts, the BAL fluid CD8+CD31+ T lymphocyte and CD8+ CD103+ T lymphocyte counts, and the number of lung nodules on chest CT may be reasonable predictors of sarcoidosis progression." (PMID 37239108, 2023). "We found that of all indices tested, two immune blood T lymphocytes markers (CD4+CD31+ and CD4+CD44+), two BALF T lymphocytes markers (CD8+CD31+ and CD8+CD103+) and one chest CT sign (a number of lung nodules) are potential prognostic factors for the course of sarcoidosis." (PMID 37239108, 2023).
soft tissue sarcoma (6 papers, 2001 to 2023). A malignant neoplasm arising from muscle tissue, adipose tissue, blood vessels, fibrous tissue, or other supportive tissues excluding the bones. "The purpose of this study was to investigate the clinical significance of CD44 in adult soft tissue sarcomas (STS)." (PMID 11161384, 2001). "Thus, the authors concluded that increased expression of CD44 was correlated with worse outcomes in soft tissue sarcomas." (PMID 35785191, 2022). "Therefore, this multimodal probe may be significant in intraoperative and preoperative tumor imaging for CD44-positive bone and soft tissue sarcoma." (PMID 35860548, 2022).
testicular germ cell tumor (6 papers, 2015 to 2024). A germ cell tumor arising from the testis. "From the perspective of cancer types, CD44 was most significantly positively related to immune cell infiltration within testicular germ cell tumors (TGCTs)." (PMID 38590654, 2024). "Our study showed an increase in the expression frequency of GLUT1 and CD44 in adult testicular germ cell tumors." (PMID 31316469, 2019). "Association of CD44, GLUT1 and CAIX membrane expression and cytoplasmic expression of HKII and LDHV with clinicopathological characteristics of adult testicular germ cell tumors." (PMID 31316469, 2019). "Immuhistochemical evaluation of adult testicular germ cell tumors showed that expression of CD44, GLUT1 and CAIX was mostly exclusively found in plasma membrane." (PMID 31316469, 2019). "Then, we examined the mRNA and protein expression levels of CD44 in germ cell tumor cell lines." (PMID 38796656, 2024). "According to our results, CD44 showed positive relation to following factors: main immune checkpoints of testicular germ cell tumor (TGCT), ACC, KICH, LGG, LIHC, LUAD, and OV; TMB values of COAD, LGG, and UCEC; and MSI values of COAD, READ, and UCEC." (PMID 38590654, 2024). "The miR-372 and miR-373 miRNA cluster were originally associated with stemness in embryonic cells and oncogenicity in human testicular germ cell tumors via a concomitant targeting of LATS2 and CD44." (PMID 25714028, 2015). "It was then found that they act as oncogenes during the tumorigenesis of human testicular germ cell tumors by concomitant targeting of LATS2 and CD44 in order to overcome senescence and to promote metastasis, respectively." (PMID 25714028, 2015).
thyroid tumor (6 papers, 2010 to 2025). A benign or malignant neoplasm affecting the thyroid gland. "CD44 was expressed in prospectively identified thyroid tumour-initiating cells that induce tumours when injected orthotopically into mouse thyroid." (PMID 27811013, 2016). "Some internal validations emerged, such as the pairs PLAU/PLAUR, SPP1/CD44, and SPP1/ITGA9, whose ligands have been demonstrated overexpressed in thyroid tumors as well as in our in vitro model." (PMID 20877637, 2010). "Additionally, based on the PCR result, several inflammatory factors, such as Survivin, CD44, NF-kappaB, and IL-6, were higher expressed in the EBV-positive groups, and the mRNA expression of EBER1 and EBER2 was higher in thyroid tumor group." (PMID 31134145, 2019).
type 1 diabetes (6 papers, 2013 to 2022). "CD44 may be involved in aberrant signaling pathways leading to apoptosis not only in lymphocytes but also in other cells, for example, in β cells in type 1 diabetes." (PMID 32517153, 2020). "We have previously shown that injection of anti-CD44 antibody into NOD mice induced resistance to type 1 diabetes (T1D)." (PMID 26624007, 2015).